TPH1 (tryptophan hydroxylase 1)
Diseases named in the same sentence as TPH1 in open-access papers (continued):
Sharing a sentence is not in itself a finding about the gene and the disease.
glioma (continued). "Collectively, these findings highlighted that TPH-1 mediated tryptophan hydroxylation could produce serotonin, thereby promoting glioma progression." (PMID 35473609, 2022). "Notably, an increased mRNA expression of L1CAM was observed in the TPH-1 high glioma cancer tissues, and L1CAM reportedly serves as an L1 cell adhesion molecule, thereby participating in the process of cellular migration of tumor cells." (PMID 35473609, 2022). "Moreover, TPH-1 blockade produced a substantial suppression of tumor growth in a mouse model of glioma when administered in conjunction with chemotherapeutic agents." (PMID 35473609, 2022). "Notably, TPH-1 overexpression significantly promoted cellular proliferation and migration of glioma cells." (PMID 35473609, 2022). "Moreover, our data linked TPH-1 to the chemotherapeutic sensitivity of glioma, demonstrating that TMZ resistance was aggravated in the LN229/T98G cells overexpressing TPH-1." (PMID 35473609, 2022). "Mechanistically, TPH-1 increased the production of serotonin in glioma cells." (PMID 35473609, 2022). "Importantly, we have highlighted the involvement of L1CAM in TPH-1 mediated glioma progression, as indicated by the upregulation of L1CAM in THP1 overexpressing glioma cells." (PMID 35473609, 2022). "In addition, data from the in vitro experiments showed that TPH-1 facilitated glioma cell proliferation and decreased the efficacy of chemotherapy by catalyzing the production of serotonin." (PMID 35473609, 2022). "Targeting TPH-1 may open new avenues for the clinical treatment of glioma." (PMID 35473609, 2022). "In conclusion, we demonstrated that TPH-1 functioned through the serotonin/L1CAM/NF-κB pathway, thus facilitating glioma cell proliferation, migration, and chemoresistance." (PMID 35473609, 2022). "Therefore, targeting TPH-1 may be a feasible modality for curing glioma." (PMID 35473609, 2022). "To assess the potential relevance of TPH-1 in glioma development, first, we evaluated the transcriptomic expression of TPH-1 in 156 glioma tissues and compared them to those in the normal tissues using TCGA database." (PMID 35473609, 2022). "In addition, TPH-1 overexpressing LN229/T98G cells exhibited enhanced resistance to the chemotherapeutic agent, TMZ, suggesting that a high level of TPH-1 resulted in enhanced tumor growth and reduced chemo-sensitivity in glioma." (PMID 35473609, 2022).
Glucose intolerance (3 papers, 2014 to 2020). Glucose intolerance (GI) can be defined as dysglycemia that comprises both prediabetes and diabetes. "On the contrary, β-cell-specific Tph1 knockout mice displayed glucose intolerance and impaired insulin secretion with aging." (PMID 32641996, 2020). "Tph1 depletion might lead to age-related glucose intolerance because of β-cell functional decompensation." (PMID 32641996, 2020). "Moreover, inhibition of Tph1 or Htr2b blocked normal increase of β-cell mass during pregnancy and resulted in glucose intolerance in mice." (PMID 24337628, 2014).
Hyperglycemia (3 papers, 2020 to 2023). An increased concentration of glucose in the blood. "To further strengthen the significance of our results, we investigated the effect of hyperglycemia on the expression of SERT, TPH1 and MAOA genes at ambient (21%) oxygen levels." (PMID 37371714, 2023). "Our results show similar effects of hyperglycemia when compared to either osmotic control or normoglycemic control (Figure A1), suggesting that the expression of SERT, TPH1 and MAOA was directly affected by high glucose, and not elevated osmotic pressure." (PMID 37371714, 2023).
idiopathic scoliosis (3 papers, 2016 to 2021). A scoliosis with no known cause. "The aim of the current study is to investigate the association between the promoter polymorphism TPH1 (rs10488682) and progression of idiopathic scoliosis (IS) in Eastern European population sample." (PMID 27293961, 2016).
prostate carcinoma (3 papers, 2022 to 2025). A carcinoma that arises from epithelial cells of the prostate gland. "We further explored the underlying mechanism of TPH1-induced prostate cancer progression." (PMID 36172162, 2022). "In this study, we reported that the overexpression of Trp hydroxylase 1 (TPH1) caused the upregulation of Trp hydroxylation and mediated the production of 5-hydroxytryptamine (5-HT), contributing to tumor growth and poor prognosis in patients with prostate cancer." (PMID 36172162, 2022). "Blocking TPH1 activity with 4-chloro-DL-phenylalanine interrupts this cycle, reducing tumor growth and strengthening the effect of paclitaxel in prostate-cancer models." (PMID 41375042, 2025). "The targeting of TPH1 led to a stronger anticancer effect and suppression of distant metastasis, providing innovative insights for prostate cancer therapy." (PMID 36172162, 2022). "The activation of β-catenin signals is critical in diverse tumor types, and we further observed that β-catenin mediates the upregulation of TPH1 in prostate cancer, forming the 5-HT/β-catenin/TPH1 signaling loop." (PMID 36172162, 2022). "In our study, we initially confirmed the role of TPH1 in tumor development, in which TPH1 catabolized Trp to 5-HT and promoted prostate cancer proliferation/migration." (PMID 36172162, 2022). "Interruption of the 5-HT/β-catenin/ZBP-89/TPH1 signaling loop by the 5-HT inhibitor significantly suppresses prostate cancer development." (PMID 36172162, 2022). "To assess the level of Trp metabolism, or more specifically, the role of TPH1 in the development of prostate cancer, we examined the expression of TPH1 in prostate tumor tissues." (PMID 36172162, 2022). "This indicated the potential presence of a 5-HT/β-catenin/ZBP-89/TPH1 signaling feedback loop in prostate cancer." (PMID 36172162, 2022). "In conclusion, our findings demonstrated that Trp hydroxylation induced by TPH1 plays an essential role in prostate cancer development, which was dependent on a 5-HT/β-catenin/ZBP-89/TPH1 signaling loop." (PMID 36172162, 2022). "As anticipated, TPH1 overexpression significantly promoted the migration of DU145 and PC-3 cells, indicating that TPH1 promoted the potential for cell migration in prostate cancer." (PMID 36172162, 2022). "Intriguingly, the upregulation of β-catenin signaling induced by TPH1/5-HT also promoted cell migration and metastasis in prostate cancer." (PMID 36172162, 2022). "Collectively, the results suggested that the interruption of the 5-HT/β-catenin/ZBP-89/TPH1 signaling loop by the THP1 inhibitor PCPA efficiently improved the outcome of prostate cancer therapy; this finding constitutes a novel perspective in tumor treatment." (PMID 36172162, 2022). "Given the crucial role of the 5-HT/β-catenin/ZBP-89/TPH1 signaling loop in prostate cancer development, interrupting the TPH1 signaling loop for improving the tumor-suppressive effects in TPH1 overexpression in prostate cancer may be possible." (PMID 36172162, 2022). "This prompted us to consider that TPH1 may mediate Trp hydroxylation and produce 5-HT to stimulate prostate cancer development." (PMID 36172162, 2022). "Furthermore, we sought to assess the influence of TPH1 on the overall survival of patients with prostate cancer." (PMID 36172162, 2022). "Furthermore, Trp metabolism and 5-HT levels were presumably elevated in TPH1-overexpressing DU145/PC-3 cells, which caused the sustained proliferation of prostate cancer cells." (PMID 36172162, 2022). "Interestingly, a negative correlation was observed between the survival time and TPH1 expression in patients with prostate cancer." (PMID 36172162, 2022). "This indicated that TPH1 may promote the proliferation of prostate cancer cells to induce tumor progression." (PMID 36172162, 2022).
prostate carcinoma (continued). "Consistent with our hypothesis, Trp metabolism and 5-HT levels were higher in TPH1-overexpressing DU145/PC-3 cells than in the vector groups, suggesting that TPH1 facilitated Trp hydroxylation in prostate cancer cells." (PMID 36172162, 2022). "Similarly, ZBP-89 inhibition caused the downregulation of TPH1 in 5-HT–treated cells, indicating that β-catenin and ZBP-89 cooperated to mediate the upregulation of TPH1, thus forming a positive feedback loop to drive prostate cancer development." (PMID 36172162, 2022). "The enzyme tryptophan hydroxylase 1 (TPH1) converts tryptophan into serotonin, which in prostate cancer cells activates growth- and survival-related signaling." (PMID 41375042, 2025). "The prostate cancer cells DU145 and PC-3 exhibit stronger proliferative characteristics when TPH1 was overexpressed." (PMID 36172162, 2022). "Our findings revealed a mechanism by which TPH1 promotes prostate cancer growth by inducing Trp hydroxylation and identified a novel THP1 target for an innovative prostate cancer therapeutic strategy." (PMID 36172162, 2022).
systemic lupus erythematosus (3 papers, 2024 to 2025). An autoimmune multi-organ disease typically associated with vasculopathy and autoantibody production. "Study found that Tph1 and Tph17 cells showed B-helper functions, while Tph2 cells exhibited cytotoxic activity in systemic lupus erythematosus patients." (PMID 40599793, 2025).
anemia (2 papers, 2013 to 2022). A reduction in the number of red blood cells, the amount of hemoglobin, and/or the volume of packed red blood cells. "We have recently confirmed in our Tph1 (−/−) colony that these mice have mild anemia, as previously reported however, it is unlikely to affect their gait." (PMID 23516593, 2013).
carcinoid (2 papers, 2017 to 2025). "As with pulmonary endothelium in PAH, carcinoid tumors produce large amounts of 5-HT through the over-expression TPH1 – the rate limiting step in 5-HT synthesis." (PMID 28529483, 2017). "Whole cell activity of TPH1 inhibition was assessed using BON cells (human carcinoid cell line) within a newly designed in vitro assay where new synthesiszed 5-HT could be detected via the labeling of tryptophan substrate with deuterium." (PMID 28529483, 2017). "We demonstrate 15-fold greater potency within a human carcinoid cell line versus the most potent known TPH1/2 non-specific inhibitor." (PMID 28529483, 2017).
Constipation (2 papers, 2022 to 2023). Infrequent or difficult evacuation of feces. "In a constipation rat model induced by loperamide, treatment with Bifidobacterium bifidum ameliorated symptoms of constipation, and increases in the 5-HT and Tph1 mRNA levels were observed." (PMID 37333632, 2023).
eating disorder (2 papers, 2009 to 2025). A broad group of psychological disorders with abnormal eating behaviors leading to physiological effects from overeating or insufficient food intake. "Another related objective was to explore the association between the psychopathology of obsessionality and eating disorders and the TPH1 A 218C polymorphism using psychological measurements." (PMID 20046373, 2009). "In the present study, the first aim was to investigate whether the TPH1 A218C polymorphism was associated with eating disorders using a case-control design." (PMID 20046373, 2009). "Therefore, we investigated whether a genetic variant of the TPH1 gene is associated with eating disorders with particular emphasis on obsessionality." (PMID 20046373, 2009). "We examined the association between the tryptophan hydroxylase 1 (TPH1) gene and eating disorders focusing on obsessionality." (PMID 20046373, 2009). "The TPH1 A218C genotype distribution was in Hardy-Weinberg equilibrium in the patients with eating disorders and healthy participants (χ2=2.01, df=2, p=0.16), BN (χ2=1.77, df =2, p=0.18) and AN (χ2=0.54, df=2, p=0.46)." (PMID 20046373, 2009).
lung fibrosis (2 papers, 2016 to 2018). "In the present study, we exhibited direct experimental results demonstrating that wild-type C57BL/6 mice (sufficiency of peripheral 5-HT) were more susceptible to bleomycin-induced pulmonary fibrosis compared with TPH1 knockout mice (deficiency of peripheral 5-HT)." (PMID 29849496, 2018). "Monitoring of 5-HT synthesis was demonstrated to enable medium through-put testing of TPH1 inhibitors in vivo and was used to explore the mechanism of 5-HT dysregulation in a bleomycin-induced model of lung fibrosis." (PMID 27444653, 2016). "In the bleomycin-lung fibrosis rat model, total lung 5-HT and new 5-HT synthesis (h-5-HT) were significantly correlated with lung Tph1 mRNA, strongly suggestive of a contribution from local synthesis." (PMID 27444653, 2016). "The aim of this study was to investigate the role of 5-HT in bleomycin- (BLM-) induced pulmonary fibrosis through wild-type C57BL/6 (WT) and TPH1 knockout (KO) mouse experiments." (PMID 29849496, 2018). "In conclusion, our preclinical study using TPH1 knockout and wild-type C57BL/6 mice demonstrated that 5-HT markedly exacerbated bleomycin-induced lung fibrosis." (PMID 29849496, 2018).
lymphocytic colitis (2 papers, 2018 to 2021). Microscopic colitis characterized by the accumulation of lymphocytes in the colonic epithelium and lamina propria. "In conclusion, lymphocytic colitis can be associated with increased levels of 5-HT, which may result from an increased number of EC cells within increased EECs population and an increased expression of TPH1, a rate-limiting enzyme in 5-HT production." (PMID 33466782, 2021).
nicotine addiction (2 papers, 2004 to 2015). "Mutations on TPH1 are associated with an elevated risk for a variety of diseases and disorders, including, somatic anxiety, suicidal behavior, and nicotine addiction." (PMID 26111525, 2015).
squamous cell carcinoma (2 papers, 2021 to 2025). A carcinoma arising from squamous epithelial cells. "All had characteristic interferon-ω autoantibodies, while most also had broader autoreactivity, including IL-22, 17α-hydroxylase, 21-hydroxylase, aromatic L-amino acid decarboxylase (AADC), tryptophan hydroxylase 1 (TPH1), SOX10, NALP5 and squamous cell carcinoma (SCC) antibodies." (PMID 41009535, 2025).
Thromboembolism (2 papers, 2021 to 2024). The formation of a blood clot inside a blood vessel that subsequently travels through the blood stream from the site where it formed to another location in the body, generally leading to vascular occlusion at the distant site. "TPH1 deficient mice were found to lack peripheral serotonin synthesis, thus showing diminished thrombosis and thromboembolism risk." (PMID 34680558, 2021).
vitiligo (2 papers, 2014 to 2016). Generalized well circumscribed patches of leukoderma that are generally distributed over symmetric body locations and is due to autoimmune destruction of melanocytes. "Patients with inherited vitiligo have been shown to have significantly lower TPH1 expression, leading to low serotonin levels after Epidermal H2O2/ONOO(-)-mediated stress." (PMID 24586946, 2014).
acute pancreatitis (1 paper, 2021). An acute inflammatory process that leads to necrosis of the pancreatic parenchyma. "In the present study, we investigated the association of the TPH1 gene polymorphism rs211105 (T/G) with acute pancreatitis and tryptophan hydroxylase 1 concentrations in circulation." (PMID 34772352, 2021). "This study aimed to explore the association of a rs211105 (T/G) polymorphism in TPH1 gene with tryptophan hydroxylase 1 concentrations in blood serum in a population of acute pancreatitis patients, and to investigate this association with acute pancreatitis susceptibility." (PMID 34772352, 2021).
allergic asthma (1 paper, 2024). A asthma with a basis in a pathological type I hypersensitivity reaction. "Then, we further analyzed three Tph subtypes and found a lower frequency of Tph1 subtypes while a higher frequency of Tph2 and Tph17 subtypes in children with allergic asthma than those of HC." (PMID 38424520, 2024). "Further analysis showed increased Tph2, Tph17, Tfh2 and Tfh17 subtypes while decreased Tph1 and Tfh1 subtypes in children with allergic asthma." (PMID 38424520, 2024).
atherosclerosis (1 paper, 2021). A disease characterized by the build-up of fatty material and calcium deposition in the arterial wall resulting in partial or complete occlusion of the arterial lumen. "Our results suggest that reduction of vascular 5-MTP in HFD-induced atherosclerosis is attributed to suppression of TPH-1 expression." (PMID 34749728, 2021). "It is possible that TLR2/4 activation suppress TPH-1 expression at the transcriptional level in HFD-induced atherosclerosis." (PMID 34749728, 2021).
ductal carcinoma in situ (1 paper, 2009). "Staining for TPH1 was lower in locally-invasive (IN+) cases compared with non-invasive samples (NI), which included both normal tissue and ductal carcinoma in situ (DCIS)." (PMID 19903352, 2009).
edema (1 paper, 2020). An abnormal accumulation of fluid beneath the skin, or in one or more cavities of the body. "Taken together, it is reasonable to speculate that chronic hypoxia from pulmonary edema may be one of the factors that induce an increased expression of TPH1 in DMVD dogs." (PMID 33426031, 2020).
glioblastoma (1 paper, 2024). The most malignant astrocytic tumor (WHO grade IV). "The overexpression of tryptophan hydroxylase 1 (TPH1), an enzyme limiting peripheral 5-HT synthesis, in two cellular lines derived from human glioblastomas (LN229 and T98G), increased proliferation, migration, and expression of genes involved in cellular adhesion, while diminishing apoptosis." (PMID 39153092, 2024).
Hyperphenylalaninemia (1 paper, 2024). "These mice show reduced levels and activity of PAH, TPH2, and TPH1 in liver, brain, and pineal gland, respectively, and experience hyperphenylalaninemia and central and peripheral serotonin deficiency." (PMID 39695187, 2024).
idiopathic pulmonary arterial hypertension (1 paper, 2022). A sporadic form of pulmonary arterial hypertension (PAH) characterized by elevated pulmonary arterial resistance leading to right heart failure. "In rat models, tph1 expression was found to be dependent on the different PH phenotypes, with tph1 upregulated in idiopathic pulmonary arterial hypertension, while expression did not change in hypoxic PH rats compared to normal rats." (PMID 36288144, 2022).
intestinal infections (1 paper, 2025). "To explore the impact of FAEW on neuroendocrine signaling related to intestinal infections and bloating, we examined the gene expression of key components in the serotonin biosynthesis pathway (tph‐1), the DAF‐7/TGF‐β pathway (daf‐7), and the NPR‐1/GPCR pathway (npr‐1, flp‐18, and flp‐21)." (PMID 40008431, 2025).
itch (1 paper, 2022). "Pruritogens, including TAC1, IL-2, IL-31, TPSAB1, TPSB2, and TPSG1, and the key enzymes that are attributed to itch, including HDC and TPH1, were detected by RNA-seq." (PMID 35632808, 2022).
leukemia (1 paper, 2025). A malignant (clonal) hematologic disorder, involving hematopoietic stem cells and characterized by the presence of primitive or atypical myeloid or lymphoid cells in the bone marrow and the blood. "Moreover, SLC40A1 also has a functional ERE located in its promoter, and estrogen decreased the expression of ferroportin in the TPH1 cell line (human leukemia monocytic cell) and in macrophages." (PMID 41303636, 2025).
liver cancer (1 paper, 2021). An epithelial or non-epithelial malignant neoplasm that arises from the liver. "Interestingly, compared with TPH1 + PMA + L02-SCR group, it is showed for the M2 polarization in TPH1 + PMA + L02-Sh group and TPH1 + PMA + IL-4 + IL-13 group, indicated decreased FPN1 promoted liver cancer cell M2 polarization." (PMID 34183746, 2021).
liver fibrosis (1 paper, 2022). "Based on this, we speculate that intestinal flora disorders caused by liver fibrosis may inhibit the activity of TPH1, thus hindering the normal metabolism of tryptophan and leading to an abnormal increase in 5-hydroxy-L-tryptophan." (PMID 36676934, 2022). "Therefore, we speculate that TACS may reduce liver fibrosis by indirectly increasing the level of tryptophan through regulating TPH1 activity and restoring the level of 5-hydroxy-L-tryptophan." (PMID 36676934, 2022).